EZR (ezrin)
Diseases named in the same sentence as EZR in open-access papers (continued):
Sharing a sentence is not in itself a finding about the gene and the disease.
Encephalopathy (1 paper, 2019). Encephalopathy is a term that means brain disease, damage, or malfunction. "Regarding pathology, a striking feature is the ezrin-staining of vessel-associated astrocytes in severe encephalopathy." (PMID 31382374, 2019). "However, it appears more likely, that ezrin up-regulation in HIV-encephalopathy is associated with a specific state of astrocyte activation." (PMID 31382374, 2019).
endometrial adenocarcinoma (1 paper, 2022). "Therefore, new drug modalities targeting ezrin may be effective for reducing the PD-L1 expression on the cell surface of human endometrial adenocarcinoma and providing a novel therapeutic option to enhance the response rate of ICB therapies." (PMID 35456317, 2022).
enteropathy (1 paper, 2025). "Our clinical and cell biological observations lead us to conclude that ezrin deficiency may be associated with severe enteropathy in humans, of congenital onset as in the patient we report here." (PMID 40137958, 2025). "The idea of an early-onset, severe enteropathy is strongly supported by both constitutional and conditional ezrin deletion studies in mice." (PMID 40137958, 2025).
follicular adenoma (1 paper, 2019). "In FTC, intense expression of ezrin was observed in both cytoplasm and membrane when compared to the moderate cytoplasmic staining of ezrin in follicular adenoma." (PMID 30996241, 2019).
gastrointestinal carcinoma (1 paper, 2012). "Recently, it has been shown that Ezrin plays a pivotal role in the progression of gastrointestinal carcinoma." (PMID 23039327, 2012).
giant cell tumor of bone (1 paper, 2015). "This research aimed to study the role of ezrin, CD44, and VEGF in invasion, metastasis, recurrence, and prognosis of giant cell tumor of bone (GCTB) and its association with the clinical and pathological features of GCTB." (PMID 25929323, 2015).
Giardia infection (1 paper, 2022). "The expression and the cellular distribution of actin filaments (i.e., F-actin and alpha-actinin) as well as actin-binding proteins (i.e., villin and ezrin) are altered following Giardia infection, leading to compromised intestinal epithelial integrity." (PMID 35250996, 2022). "The decreased levels of ezrin phosphorylation as well as increased levels of phosphorylated villin correlated with reduced BB disaccharidase enzymes (i.e., sucrase, maltase) activity observed during Giardia infection." (PMID 35250996, 2022). "Notably, ezrin and villin were found to be differentially regulated by immune-mediated mechanisms following Giardia infection; while ezrin proteolysis required CD4+ T cells alone, the cleavage of villin required both CD4+ and CD8+ T cell responses." (PMID 35250996, 2022).
gonococcal infection (1 paper, 2011). "With gonococcal infection, mature plaques are formed after 2–4 h post infection and the density of plaque proteins including ezrin increased during this time period (Höne & Maier, unpublished)." (PMID 21340023, 2011).
head and neck cancer (1 paper, 2016). A primary or metastatic malignant neoplasm affecting the head and neck. "In a follow up study, 131 samples from head and neck cancer patients were further evaluated for ezrin, moesin, merlin and willin, recording levels of expression and also cellular distribution of cytoplasmic, membranous or nuclear." (PMID 27438856, 2016). "Collaborators had identified that the cytoplasmic distribution of ezrin could predict the outcome of particular head and neck cancer studies, and as such act as a prognostic marker for these tumours." (PMID 27438856, 2016).
hemangioblastoma (1 paper, 2025). "Hemangioblastomas are usually positive for alpha-inhibin, D2-40, brachyury, NSE, NCAM1, S100, ezrin, CXCR4, aquaporin-1, and occasionally for GFAP and EGFR, and negative for EMA, CD10 and CAM5.2." (PMID 41302074, 2025).
hepatitis C virus infection (1 paper, 2023). A viral infection caused by the hepatitis C virus. "Since HepaRG cells have been isolated from a Hepatitis C Virus infection-associated liver tumor, depicting both hepatocyte-like and cholangiocyte-like phenotypes, we wanted to exclude tumor-associated Ezrin expression." (PMID 37928027, 2023).
inflammatory bowel disease (1 paper, 2021). A spectrum of small and large bowel inflammatory diseases of unknown etiology. "The modification of this ezrin peptide doubles the anti-inflammatory activity of RepG3 2× over Gepon, in a mouse dextran sulphate solution (DSS) gut inflammation model that mimics inflammatory bowel disease (IBD)." (PMID 34769119, 2021).
influenza (1 paper, 2017). An acute viral infection of the respiratory tract, occurring in isolated cases, in epidemics, or in pandemics; it is caused by serologically different strains of viruses (influenzaviruses) designated A, B, and C, has a 3-day incubation period, and usually lasts for 3 to 10 days. "Our previous study also provided evidence for the involvement of Rho/ROCK and PKC pathways in influenza-induced hyperpermeability in microvascular cells via phosphorylating Ezrin/Radixin/Moesin (ERM)." (PMID 29059211, 2017).
Insulin resistance (1 paper, 2022). Increased resistance towards insulin, that is, diminished effectiveness of insulin in reducing blood glucose levels. "Whether ezrin contributes towards overcoming insulin resistance usually in obese subjects is as yet unknown." (PMID 35807067, 2022).
intrahepatic cholangiocarcinoma (1 paper, 2019). A carcinoma that arises from the intrahepatic bile duct epithelium in any site of the intrahepatic biliary tree. "However, Ezrin expression has also been reported to be down-regulated in human intrahepatic cholangiocarcinoma, and its loss was shown to result in a more aggressive phenotype." (PMID 30804430, 2019).
invasive carcinoma (1 paper, 2023). A carcinoma that is not confined to the epithelium, and has spread to the surrounding stroma. "The expression of phosphorylated ezrin (p-ezrin, tyr354) is higher significantly in IPMN than in invasive carcinoma." (PMID 36874143, 2023).
Keratocystic odontogenic tumor (1 paper, 2014). An intraosseous odontogenic neoplasm that usually arises from the mandible. "The Spearman test did not demonstrate statistically significant correlation between membranous or cytoplasmic podoplanin and ezrin expressions in keratocystic odontogenic tumors." (PMID 25480364, 2014). "The distribution of ezrin in odontogenic keratocystic tumors was more heterogeneous than that of podoplanin and statistically significant differences were observed among the localization of membranous ezrin and cytoplasmic or membranous podoplanin." (PMID 25480364, 2014). "The aims of this study were to investigate the immunolocalization of ezrin and its relationship with the podoplanin expression in keratocystic odontogenic tumors." (PMID 25480364, 2014). "So, in order to verify if podoplanin and ezrin are co-localized in keratocystic odontogenic tumors, we designed the present study." (PMID 25480364, 2014). "Our results showed strong cytoplasmic ezrin and membranous podoplanin expressions in basal epithelial layer of all keratocystic odontogenic tumors." (PMID 25480364, 2014). "The podoplanin activated form (membranous) was mostly found in the basal layer, indicating a co-localization of active-ezrin and active-podoplanin in the highly active areas of keratocystic odontogenic tumors." (PMID 25480364, 2014). "The currently study was designed to analyze the immunolocalization of ezrin and its relationship with podoplanin expression in keratocystic odontogenic tumors." (PMID 25480364, 2014). "The immunohistochemical expressions of ezrin and podoplanin by odontogenic epithelium were evaluated in keratocystic odontogenic tumors using monoclonal antibodies." (PMID 25480364, 2014). "In summary, we first report that ezrin presents strong membranous expression in the supra-basal layer and strong cytoplasmic expression in the basal layer of keratocystic odontogenic tumors." (PMID 25480364, 2014). "Thus, our investigation suggests a role for ezrin and podoplanin in keratocystic odontogenic tumors and their molecular interactions need to be further explored in these kinds of tumors." (PMID 25480364, 2014). "The results presented here showed absence of membranous ezrin in 55.56% of keratocystic odontogenic tumors and, when present, this protein was mainly observed in the membrane of the non-proliferative supra-basal layers." (PMID 25480364, 2014).
kidney cancer (1 paper, 2021). Primary or metastatic malignant neoplasm involving the kidney. "Considering that we did not observe any major changes in the mRNA levels of moesin and ezrin in the human kidney cancers, we decided to analyze the TCGA data set for the presence of potential mutations on moesin and ezrin." (PMID 34503512, 2021). "Interestingly, the expression levels of neither moesin nor ezrin were altered in a statistically significant manner in any of the kidney cancer types." (PMID 34503512, 2021).
laryngeal squamous cell carcinoma (1 paper, 2012). A squamous cell carcinoma that arises from the larynx. "Fascin-1, ezrin and paxillin, cytoskeleton-associated proteins, have been implicated in several human cancers, but their role in laryngeal squamous cell carcinoma (LSCC) is unknown." (PMID 23209815, 2012).
leiomyosarcoma (1 paper, 2011). An uncommon, aggressive malignant smooth muscle neoplasm, usually occurring in post-menopausal women. "Moreover, one ezrin-positive leiomyosarcoma patient included in our study had 14.2 month OS, compared to the median 8.2 months of four ezrin-negative ones." (PMID 21785570, 2011).
liver disease (1 paper, 2024). "CTCs were isolated from the peripheral blood of 20 HCC patients and 18 patients with nonmalignant liver disease (NMLD) via an OncoQuick® kit and immunostained with Ezrin-Alexa Fluor 488®, CD146-PE, and CD45-APC." (PMID 39791707, 2024).
malignant glioma (1 paper, 2019). A grade III or grade IV glioma arising from the central nervous system. "Neuropathological findings suggest a major role for ezrin in the development and progression of malignant glioma which has been associated with several distinct functions of ezrin." (PMID 31382374, 2019).
membranous nephropathy (1 paper, 2017). "In experimental membranous nephropathy in rats, proteinuria and GEC/podocyte injury were associated with increased glomerular SLK activity and ezrin phosphorylation." (PMID 28475647, 2017).
mesothelioma (1 paper, 2015). A usually malignant and aggressive neoplasm of the mesothelium which is often associated with exposure to asbestos. "The mTOR pathway is involved in ezrin- induced malignant phenotype, moreover the mTOR inhibition has shown antitumor effect in mesothelioma preclinical models." (PMID 25952930, 2015).
multiple sclerosis (1 paper, 2023). A progressive autoimmune disorder affecting the central nervous system resulting in demyelination. "LIPS has even been used to rule out the presence of some autoantibodies in certain diseases including against KIR4.1 in multiple sclerosis, IL-2 in T1D, and ezrin in pancreatic ductal cancer." (PMID 36979515, 2023).
muscle atrophy (1 paper, 2023). The loss of muscle tissue due to inactivity or disease. "First, we found that Ezrin was a candidate target for the treatment of muscle atrophy by promoting the regeneration and repair of the damaged gastrocnemius muscle induced by peroneal nerve injury, especially in CMT4F-associated muscle atrophy." (PMID 36870952, 2023).
muscular atrophy (1 paper, 2023). "PNI-induced muscular atrophy showed the traits of demyelination and associated muscular atrophy, similar to the changes caused by L-periaxin deletion or mutation and Ezrin-mediated L-periaxin self-association inhibition." (PMID 36870952, 2023).
myeloma (1 paper, 2013). "Interestingly, in that study T567D ezrin induced capping of CD44, but not uropod formation in a naturally unpolarized myeloma cell line, indicating that in these cells the machinery for uropod formation is lacking, in contrast to the T cells used in our study." (PMID 23579783, 2013).
myocarditis (1 paper, 2019). Myocarditis is a condition that is characterized by inflammation of the heart muscle (myocardium). "In addition, we demonstrate that the induction of acute myocarditis involves the engagement of CD43 cytoplasmic tripeptide sequence KRR to ezrin-radixin-moiesin cytoskeletal proteins." (PMID 31197200, 2019).
odontogenic tumors (1 paper, 2014). "Most of keratocyst odontogenic tumors epithelial cells (83.33% of cases) strongly expressed cytoplasmic ezrin." (PMID 25480364, 2014). "Furthermore, most of the odontogenic tumors (83.33%) showed strong cytoplasmic ezrin expression especially in the basal layer of odontogenic epithelium." (PMID 25480364, 2014). "Interestingly, the keratocystic odontogenic tumors presented strong membranous podoplanin and cytoplasmic ezrin expression, which correspond to the activated forms of both proteins." (PMID 25480364, 2014). "Although the odontogenic cell motility induced by podoplanin may be dependent on its interaction with the activated ezrin, the connection between both proteins has not previously been studied in odontogenic tumors." (PMID 25480364, 2014).
Opportunistic infection (1 paper, 2021). An infection that is caused by a pathogen that would generally not be able to cause an infection in a host with a normal immune system. "Human Ezrin Peptide One (HEP1) TEKKRRETVEREKE (brand name Gepon, registered for human use in Russia from 2001) is a successful treatment for opportunistic infections in HIV-infected patients." (PMID 34769119, 2021).
osteoarthritis (1 paper, 2025). A noninflammatory degenerative joint disease occurring chiefly in older persons, characterized by degeneration of the articular cartilage, hypertrophy of bone at the margins and changes in the synovial membrane. "This encoded ezrin protein is known to interact with CD44, a significant contributor to osteoarthritis progression." (PMID 40406113, 2025).
ovarian tumors (1 paper, 2016). "Ezrin and p130Cas expression was additionally measured in clinical specimens of OC effusions, the ovarian tumors and solid metastases." (PMID 27622508, 2016). "Subsequently, clinical specimens of high-grade serous carcinoma effusions, ovarian tumors and solid metastases were analyzed for ezrin and p130Cas expression." (PMID 27622508, 2016).
papilloma (1 paper, 2016). A benign epithelial neoplasm that projects above the surrounding epithelial surface and consists of villous or arborescent outgrowths of fibrovascular stroma. "The subcellular localization of moesin, ezrin and NF2 in CP papilloma was similar to that from normal CP." (PMID 27229317, 2016).
Parkinsonism (1 paper, 2025). Characteristic neurologic anomaly resulting from degeneration of dopamine-generating cells in the substantia nigra, a region of the midbrain, characterized clinically by shaking, rigidity, slowness of movement and difficulty with walking and gait. "Here, we found that the most common Parkinsonism gene mutation, LRRK2 G2019S, enhances the phosphorylation of the ERM proteins (Ezrin, Radixin, and Moesin), components of the perisynaptic astrocyte processes in a subset of cortical astrocytes." (PMID 39253496, 2025).
pleural mesothelioma (1 paper, 2015). A neoplasm that arises from the mesothelial cells of the pleura. "We here demonstrated, for the first time to our knowledge, that pleural mesothelioma expresses activated ERM, and that the expression of its principal component ezrin is crucial for the motility and local aggressiveness of MPM cells." (PMID 25952930, 2015).
prostate (1 paper, 2022). "The data showed that Ezrin expression in 22RV1 and PC-3 cells was notably higher than that in prostate BPH cells." (PMID 35156523, 2022).
pulmonary diseases (1 paper, 2020). "Recent studies have shown that the regulation of Ezrin might be altered in pulmonary diseases." (PMID 32028718, 2020).
pulmonary hypertension (1 paper, 2023). Increased pressure within the pulmonary circulation due to lung or heart disorder. "Under conditions of hypoxia, where p-ezrin, and at later time points, NHE1 protein levels are increased, these interactions appear to facilitate changes in PASMC phenotype that would promote vascular remodeling and the development of pulmonary hypertension." (PMID 36926194, 2023).
Q fever (1 paper, 2023). A bacterial infection caused by Coxiella burnetii. "For example, CD44–ezrin interactions are involved in the internalization process of Coxiella burnetii, the etiologic agent of Q fever, in non-phagocytic cells." (PMID 37894408, 2023).
renal fibrosis (1 paper, 2014). A final common manifestation of a wide variety of chronic kidney diseases characterized by glomerulosclerosis and tubulointerstitial fibrosis. "In our study, we demonstrated that moesin, which is a member of ezrin/radixin/moesin (ERM) family, was involved in the process of renal fibrosis." (PMID 25406076, 2014).
retinitis pigmentosa (1 paper, 2022). Retinitis pigmentosa (RP) is an inherited retinal dystrophy leading to progressive loss of the photoreceptors and retinal pigment epithelium and resulting in blindness usually after several decades. "This study aimed to verify the therapeutic inhibition of Ezrin to induce clearance of toxic aggregates in a mouse model for a dominant form of retinitis pigmentosa (i.e., RHOP23H/+)." (PMID 35847673, 2022).
SARS-CoV infection (1 paper, 2012). "Expression of the dominant negative N-terminal FERM domain of ezrin in Vero E6 cells was used to investigate the consequences of ezrin function disruption on the host cell susceptibility to SARS-CoV infection and entry of SARSpp." (PMID 23185364, 2012). "Although direct evidence of the interaction occurring during early stages of SARS-CoV infection has yet to be demonstrated, our functional analysis reveals that ezrin has a limiting effect on SARS-CoV entry." (PMID 23185364, 2012). "To verify that the enhanced permissiveness to SARS-CoV infection observed in cells expressing the ezrin FERM domain is due to a higher efficiency of entry of virions, we investigated levels of transduction of control, GFP-ezrinwt and GFP-ezrinFERM clonal Vero E6 cells by SARSpp." (PMID 23185364, 2012). "When the FERM domain of ezrin was expressed, cell susceptibility to infection was enhanced with either SARS-CoV or SARSpp, further indicating that ezrin's restricting role on SARS-CoV infection takes place at the entry step." (PMID 23185364, 2012). "To further study the role of ezrin during SARS-CoV infection, we produced clonal Vero E6 stable cell lines that either express wild-type ezrin (ezrinwt) or the N-terminal FERM domain of ezrin (ezrinFERM) fused to the green fluorescent protein (GFP)." (PMID 23185364, 2012).
seminoma (1 paper, 2021). A radiosensitive malignant germ cell tumor found in the testis (especially undescended), and extragonadal sites (anterior mediastinum and pineal gland). "Of them, 14-3-3γ, ezrin, filamin A, Parkinsonism-associated deglycase 7 (PARK7), vimentin and vinculin, were validated in CS I seminoma patient cohort." (PMID 34771736, 2021). "While 14-3-3γ, ezrin, filamin A, PARK7, vinculin and vimentin could be analysed in cohort of CS I seminoma patients using IHC to validate their clinical relevance, IHC evaluation in the case of caldesmon and 14-3-3β failed (data were non-homogenous and suboptimal)." (PMID 34771736, 2021).
synovitis (1 paper, 2021). Inflammation of a synovial membrane. "To explore the effect of Ezrin expression on AIA joint synovitis and synovial vessels, we injected Ad‐Ezrin and control vector into the articular cavity of AIA mice for 6 weeks, once a week." (PMID 34459110, 2021).